LEP (leptin)
Diseases named in the same sentence as LEP in open-access papers (continued):
Sharing a sentence is not in itself a finding about the gene and the disease.
tumor (continued). "The overexpression of leptin in mice promoted tumor growth and lymph node metastasis." (PMID 40940878, 2025). "The primary hypothesis of this study is that the IHC expression of adipokines—specifically leptin, leptin-R, adiponectin, and resistin—in RCC is associated with distinct tumor characteristics and may independently predict OS in patients undergoing nephrectomy." (PMID 41010935, 2025). "Blocking leptin is promising to reduce adipocytes mediated tumor-promoting effect." (PMID 40248695, 2025). "Additionally, leptin has been shown to support angiogenesis, whereas adiponectin can trigger apoptosis in tumor cells." (PMID 41255618, 2025). "The tumor size growth was linked to blood levels of glucose, leptin, and ghrelin, while no connection was found with insulin levels in the blood." (PMID 40487761, 2025). "Moreover, the in-depth mechanism of the fructose-leptin axis in the regulation of the tumor immune microenvironment and its application in tumor immunotherapy warrant further study." (PMID 40549205, 2025). "In addition, adipose tissue in obese individuals secretes various adipokines, such as leptin and adiponectin, that can modulate inflammatory pathways and influence tumor behavior." (PMID 41586238, 2025). "Also, there was a positive correlation between leptin, tumor size and difficulty in tumor dissection." (PMID 41255618, 2025). "Leptin may also promote M2 macrophage activation and their secretion of pro-inflammatory cytokines that facilitate tumor progression and metastasis." (PMID 40227577, 2025). "Nonetheless, a better understanding of the balance between PRAT-derived leptin and adiponectin in the tumor microenvironment may open new therapeutic perspectives in this category of oncologic patients." (PMID 40227577, 2025). "Notably, GBM cells possess the capacity for autocrine leptin production, allowing locally secreted leptin to activate ObR on neighbouring or self-same tumour cells." (PMID 41586225, 2025). "Interestingly, adipokines, such as leptin and resistin, play a significant role in prostate cancer by influencing tumor growth, angiogenesis, inflammation, and metastasis, often linking obesity with increased cancer risk and progression." (PMID 39796040, 2024). "More specifically, leptin can directly and indirectly impact on inflammation and angiogenesis, while adiponectin’s role is not fully understood but appears to be related to antioxidant markers and tumor outcomes in different cancers." (PMID 38339271, 2024). "The main two adipokines found to have tumor-promoting effects are leptin and adiponectin." (PMID 38611081, 2024). "In obesity, AT produces elevated levels of estrogen, pro-inflammatory cytokines (TNFα, IL-6, IL-1β), adipokines (leptin), and EVs, which may contribute to enhanced tumor invasiveness, proliferation, and metastasis." (PMID 39697630, 2024). "Leptin can stimulate tumor cells invasion and inhibit tumor cells apoptosis." (PMID 38800384, 2024). "Moreover, CAAs also secrete leptin, a hormone known to influence the immune system, potentially facilitating tumor metastasis and immune evasion." (PMID 38899007, 2024). "Adipocytes can produce numerous adipokines, such as leptin, thus promoting tumor progression." (PMID 39192979, 2024). "Moreover, exercise increased the proliferation of tumor non-infiltrated lymphocytes, regardless of the dietary regimen, and decreased the serum levels of leptin, in both tumor-bearing and tumor-free high-fat diet-fed animals." (PMID 38164270, 2024). "Interestingly, LKB1 and LEP display opposite expression patterns across a wide panel of human LUAD tumours retrieved from the Cancer Genome Atlas (TCGA) database." (PMID 39048991, 2024). "The SIRT1/leptin axis highlights the interplay between metabolic signaling and tumor progression." (PMID 39796040, 2024). "Leptin and adiponectin play intricate roles within the tumor microenvironment." (PMID 38339271, 2024).
tumor (continued). "Leptin directly influences the proliferation, differentiation, and activity of various immune cells (such as monocytes, T cells, B cells, and macrophages) and interacts with other cytokines in the tumor microenvironment." (PMID 38571500, 2024). "These correlations suggest that the link between Upd2/leptin and tumor size is likely conserved." (PMID 39642218, 2024). "We find that the underlying mechanism imparting sensitivity to LKB1 tumours is based on a paradox; despite the high levels of energetic stress accompanying loss of LKB1 alone, we observe activation of the key energy homeostasis player leptin (LEP)." (PMID 39048991, 2024). "Furthermore, alterations in adipokines, such as visfatin, adiponectin, and leptin, play a role in immune regulation and tumor control." (PMID 38541801, 2024). "Leptin is associated with the cellular and molecular parts of TME and can be affected through direct and indirect mechanisms that could lead to tumor cell invasion and distant metastasis." (PMID 37686525, 2023). "Leptin may promote tumor growth by signaling through normal endocrine pathways: Physiologic binding of leptin to its receptors on hypothalamic neurons leads to Thyrotropin-releasing hormone (TRH) production by these cells." (PMID 36973672, 2023). "Besides its important physiological role, leptin is also involved in tumor development and progression." (PMID 37509120, 2023). "Also, leptin has been shown to activate ERα signaling and increase aromatase activity leading to excessive proliferation and migration of tumor cells." (PMID 37800138, 2023). "And SAT produces leptin and maintains insulin sensitivity, thus impairing tumor progression." (PMID 37980639, 2023). "Therefore, it is conceivable that the presence of leptin in tumor micro-environment can play a significant role on the biological mechanisms such as cell growth, invasion, and escaping apoptosis." (PMID 37600567, 2023). "In addition, leptin and IL-1 induced signals have been reported to be interrelated in many pathological conditions, such as tumor inflammation, proliferation, and angiogenesis." (PMID 38152619, 2023). "Inflammation-related cytokines, such as interleukin-6 (IL-6) and C-reactive protein (CRP), as well as changes in metabolism-related adipokines, such as adiponectin and leptin, have been shown to reflect a proinflammatory microenvironment that promotes tumor development and progression." (PMID 36670988, 2023). "As both interventions intercepted tumor development, neither leptin deficiency itself nor the starvation physiology that results drive the enhanced tumor phenotype." (PMID 37648285, 2023). "In addition, leptin, and IL-1 crosstalk signals are interrelated in many pathological conditions such as tumor inflammation, proliferation, and angiogenesis." (PMID 38152619, 2023). "Leptin promotes tumour development and progression through the promotion of cell proliferation and inhibition of apoptotic pathways mediated through Akt, mitogen-activated protein kinase (MAPK), and signal transducer and activator of transcription (STAT) pathways." (PMID 36790524, 2023). "Notably, we found that treatment with p73γ or Leptin siRNA led to extensive tumor necrosis in xenografts compared with that treated with the control scrambled siRNA." (PMID 37650871, 2023). "Hepatic leptin was higher, while IL-4 was lower in the Tumor group compared to all other groups." (PMID 36834959, 2023). "Their main disadvantage is the exclusion of the factors other than leptin that may affect cancer cells and tumor microenvironment." (PMID 37007087, 2023). "For example, leptin stimulates the activation of MMP7 (Matrix Metallopeptidase 7), causing increased signaling of ERK (Extracellular Signal Regulated Protein Kinase) and JNK (c-Jun N-Terminal Kinase) pathways, resulting in tumor invasion." (PMID 37190027, 2023).
tumor (continued). "Most studies exploring the effects of adiponectin, however, have used transplant models of advanced PDAC cells to demonstrate that activation of adiponectin signaling (e.g., with the agonist AdipoRon) decreases orthotopic tumor growth by opposing leptin action." (PMID 37648285, 2023). "Finally, we found a direct impact of leptin treatment on pro-inflammatory, angiogenic, and fibrotic factors in the tumor microenvironment." (PMID 36771423, 2023). "Similar to LDL cholesterol add-back, administering recombinant insulin, IGF1 and leptin to Capan-1 xenograft-bearing mice abolished fasting-induced enhancement of terbinafine activity and it also restored cholesterol content in the tumours." (PMID 37907500, 2023). "Whether altered leptin and/or IL-4 in tumor animals had any effect on hepatic TG and PL alterations needs to be verified in future studies." (PMID 36834959, 2023). "Whether hepatic levels of leptin and IL-4 are altered by the presence of a tumor and/or chemotherapy treatment is unknown." (PMID 36834959, 2023). "In addition, leptin has been shown to have several roles in promoting normal and tumor cell growth and migration and angiogenesis." (PMID 37512149, 2023). "In addition, it has been reported that the use of leptin-derived peptides has been shown to reduce tumor growth in CRC mouse models." (PMID 37509120, 2023). "Furthermore, another study showed that recombinant leptin expressing vaccinia virus enhanced antitumor immune responses by restoring mitochondrial metabolism in tumor-infiltrating CD8+ T cells." (PMID 37474548, 2023). "It is well-established that visceral adipose tissue in oesophagogastric junctional adenocarcinoma (OGJ) patients contributes to tumour development, progression and treatment resistance via secretion of proinflammatory cytokines, insulin, fatty acids and leptin." (PMID 36790524, 2023). "Moreover, peptide analogues located at the binding site of leptin and leptin receptor (ObR) can selectively inhibit the interaction between leptin and leptin receptor, thereby inhibiting tumor occurrence and metastasis." (PMID 37666813, 2023). "Leptin and adiponectin interact with the tumor microenvironment (TME)." (PMID 37686525, 2023). "The pro-tumoural effects of leptin are facilitated by its mitogen actions and leptin acts directly on tumour growth, migration and invasion signalling pathways or affects tissue insulin sensitivity, inflammatory responses and tumour angiogenesis to exert neoplastic effects in breast cancer." (PMID 37620316, 2023). "Leptin was found to be expressed in normal and tumor mammary epithelial cells." (PMID 37512149, 2023). "Notably, elevated levels of leptin strongly correlate with tumor angiogenesis, CSC self-renewal, and chemotherapy resistance." (PMID 37784157, 2023). "Next, we determined whether the elevated levels of p73γ and Leptin are responsible for the enhanced tumor growth by E11-KO." (PMID 37650871, 2023). "Notably, transcriptional level of ABCB1 is also increased through leptin activation from tumor-related microenvironment." (PMID 37857015, 2023). "The role of leptin in numerous neoplasms has been investigated." (PMID 35805003, 2022). "Leptin did not associate with changes in tumor burden; however, circulating IL-6 was elevated in VSG mice." (PMID 35775614, 2022). "Besides, leptin in the TME can prompt memory precursor T cell differentiation that confers a quick response upon tumor rechallenge." (PMID 36618408, 2022). "Leptin signaling also drives the activation of many oncogenic pathways leading to the increased proliferation, epithelial-mesenchymal transition, migration, and invasion of tumor cells." (PMID 36555171, 2022). "In addition, with respect to the histological types of tumour, pre- and post-treatment leptin concentrations showed a tendency to significance." (PMID 36556428, 2022).
tumor (continued). "Interestingly, AAV-Leptin administration before advanced tumor development delays tumor progression proportional to the degree of body weight loss." (PMID 35563777, 2022). "Factors released by adipocytes, represented by leptin, insulin, and IL-6, can domesticate macrophages toward the function of promoting tumor malignancy, manifested by the changes in the secretion profile of macrophages, including pro-angiogenic VEGF and pro-inflammatory IL-6." (PMID 35701840, 2022). "Thus, reduced leptin level is consistent with lower hypoxia induced by increased blood vessel normalization in GLSECKO tumor." (PMID 36381236, 2022). "Moreover, high leptin serum concentrations were shown to inhibit tumor growth and angiogenesis in vivo." (PMID 35406450, 2022). "Furthermore, the knockdown of leptin/ObR signaling facilitates an immunosuppressive microenvironment and redirects tumor growth to distant sites." (PMID 35269622, 2022). "The complicated crosstalk between obese-related adipokines, such as leptin, includes post-transcriptional gene regulation that may result in an altered miRNA transcriptome that may affect tumor proliferation, invasion, apoptosis, and angiogenesis." (PMID 35710817, 2022). "Data have indicated that leptin could play other roles in immune response, tumor invasion, and metastasis." (PMID 35563103, 2022). "Leptin’s molecular ability to target its receptor has revealed its potential to enhance drug delivery, with leptin-derived peptides showing the potential to decrease tumor growth in a CRC mouse model." (PMID 35563103, 2022). "Elevated leptin levels are thought to be involved in tumour cell growth and invasion through increased expression of vascular endothelial growth factor (VEGF) and by modulating the oestrogen receptor α (ERα), which stimulates aromatase expression and consequently increases oestrogen levels." (PMID 36556428, 2022). "In obese animals, increased tumor progression has also been demonstrated, probably due to the induction of an immunosuppressive state and effects mediated by metabolites and hormones, such as leptin." (PMID 35164764, 2022). "Additionally, leptin has been shown to stimulate matrix metalloproteinase, cyclin D1, and Mcl-1 protein expression to induce cell invasion and tumor progression." (PMID 36230617, 2022). "Interestingly, the imbalance between leptin and adiponectin is a crucial factor in promoting tumor growth." (PMID 35625629, 2022). "TNFα production in immune cells is stimulated by leptin in humans and this could be important in systemic inflammation (see ‘Avoiding immune destruction’ and ‘Tumour-promoting inflammation’)." (PMID 36038791, 2022). "According to studies, pancreatic CSCs and epithelial-mesenchymal transition (EMT) are interrelated with leptin that is an important factor in the tumor microenvironment that accelerates tumor development by triggering CSC molecular regulators, Notch, Hedgehog, Wnt/β-catenin." (PMID 37529006, 2022). "It was reported that high levels of leptin and tumor aggressiveness are correlated." (PMID 36358879, 2022). "In this study, oncolytic viruses were engineered to express leptin in tumor cells." (PMID 35203357, 2022). "Another possible mechanism involves the tumor-promoting role of leptin during hyperglycemia." (PMID 36553697, 2022). "However, obese ob/ob mice, which have a genetic deletion of the satiety hormone leptin, showed effective anti-tumour responses." (PMID 35860241, 2022). "Indeed, leptin is able to shape the tumor microenvironment, through its ability to induce migration of endothelial cells and to sustain the recruitment of macrophages and monocytes, thus exerting pro-inflammatory effects." (PMID 36361728, 2022). "Leptin increased autophagic proteins in myeloma cells and decreased the apoptotic effect of conventional drugs, such as dexamethasone or doxorubicin, melphalan, and bortezomib, in tumor cells." (PMID 35625629, 2022).
tumor (continued). "Interestingly, we also found that miR-874-3p is involved in leptin induced tumor progression in NPC." (PMID 35778755, 2022). "Engineering oncolytic viruses to express leptin can augment anti-tumor response." (PMID 35062950, 2022). "(a) Changes in metabolites in T2D patients, such as in insulin/IGF-1 and leptin/adiponectin secretion, may favor tumor development." (PMID 36553697, 2022). "In addition to the influence nutritional conditions can have on epithelial cells, adipokines regulated by nutritional conditions such as leptin can impact the mammary gland and tumor microenvironment." (PMID 35186923, 2022). "Thus, to understand if leptin is a key player in the tumor progression of NPC, we conducted a clinical study and biochemical approaches to determine if leptin levels have a causal link to NPC." (PMID 35778755, 2022). "Interestingly, the complicated crosstalk between obese-related adipokines, such as leptin, includes a post-transcriptional gene regulation and an altered miRNA transcriptome, which can play a role in tumor proliferation, invasion, apoptosis, and angiogenesis." (PMID 35710817, 2022). "In addition, such high tumor leptin expression in gastro-oesophageal adenocarcinoma is associated with better survival." (PMID 35778755, 2022). "Our data indicate that increased leptin levels but not insulin, is associated to increased tumor growth." (PMID 35361802, 2022). "Interestingly, in our study, we showed that E-cadherin positive tumours are characterised by elevated leptin concentrations after treatment." (PMID 36556428, 2022). "In summary, it was not possible to correlate the BCS with the expression of tumor estrogen and progesterone receptors, but they were associated with the expression of leptin, aromatase, and IGF-1 receptors." (PMID 36262532, 2022). "Adipose tissue is not only involved in energy storage, but also, as a major endocrine organ, participates in the formation of the tumor microenvironment by secreting various hormones and cytokines, such as leptin, adiponectin, and tumor necrosis factor alpha (TNF-α)." (PMID 36361525, 2022). "Adipocytes and their precursor cells can influence tumor behavior via various hormones, growth factors, and cytokines known as adipokines including leptin, adiponectin, IL-6, hepatocyte growth factor, autotaxin, and TNF-alpha although their exact mechanism of action has not been established." (PMID 34532758, 2022). "Additionally, a significantly higher post-treatment leptin concentration was observed in E-cadherin positive tumours (p = 0.0350)." (PMID 36556428, 2022). "Furthermore, elevated leptin expression in IBrC is thought to be involved in higher tumour grades and increased size." (PMID 36556428, 2022). "Leptin has previously been shown to induce tumor growth and may be a mediating link between adiposity and enhanced tumor growth." (PMID 35361802, 2022). "One possible explanation is that Ob-R overexpression in tumor cells might activate the leptin-Ob-R-JAK2/STAT3 axis as well as other pathways such as PI3K/AKT and MAPK producing a proliferative stage through which is more sensitive to chemotherapy." (PMID 34210055, 2021). "Finally, we showed for the first time that induction of SREBP‐1 and its target gene, FASN, plays a key role in the tumor‐promoting effects of leptin." (PMID 33226729, 2021). "In addition, LEP has been demonstrated to be involved in tumor cell attraction to the bone marrow niche and to enhance proliferation and migration of tumor cells, while adiponectin from bone marrow adipocytes most likely contributes to tumor dormancy." (PMID 34831167, 2021). "The obtained results revealed that cats with luminal B or triple-negative mammary carcinoma showed a higher leptin IHC score in the tumor glandular cells, comparing to the healthy control samples (1.93 vs. 1.34, p < 0.05; 2.00 vs. 1.34, p < 0.05, respectively)." (PMID 33644151, 2021). "Exogenous leptin administration increases tumor growth in athymic nude mice." (PMID 34389732, 2021).